RNU4-47P (RNA, U4 small nuclear 47, pseudogene)
Gene: Small nuclear RNA gene on chromosome 17 (77,152,561 to 77,152,674, reverse strand). Ensembl gene ENSG00000222808.
Homologues: Orthologues: chimpanzee U4 (96% identical), macaque U4 (90% identical), dog U4 (60% identical), tropical clawed frog U4 (57% identical), rat LOC120094538 (56% identical), pig U4 (55% identical), guinea pig U4 (54% identical), tropical clawed frog U4 (53% identical), tropical clawed frog U4 (51% identical). Paralogues in human: RNU4-50P (61% identical), RNU4-66P (61% identical), RNU4-76P (61% identical), RNU4-28P (60% identical), RNU4-15P (59% identical), RNU4-17P (59% identical), RNU4-20P (59% identical), RNU4-21P (59% identical), RNU4-30P (59% identical), RNU4-44P (59% identical), RNU4-49P (59% identical), RNU4-52P (59% identical), and 79 more.